IGF1 (insulin like growth factor 1)
Diseases named in the same sentence as IGF1 in open-access papers (continued):
Sharing a sentence is not in itself a finding about the gene and the disease.
squamous cell carcinoma (7 papers, 2010 to 2025). A carcinoma arising from squamous epithelial cells. "Lycopene intake reduced squamous cell carcinoma by inhibiting cell proliferation, cell migration, tumor growth, IGF1, IGF (BP), IGFBP3, and transcription factor Jun/Ap‐1." (PMID 40661795, 2025). "This is the first reported case in the literature of Marjolin's ulcer in LS which raises the possibility that IGF-1 deficiency does not completely protect against squamous cell cancer." (PMID 32296486, 2020). "IGF-1 has been shown to increase transepithelial electrical resistance (a measure of barrier function) by regulating occludin and claudin-3 in submandibular gland cells, zona occludens (ZO)-1 in A431 human epidermoid carcinoma cells and claudin-1 in osteoblast cells." (PMID 24618563, 2014).
systemic sclerosis (7 papers, 2013 to 2025). A chronic disorder, possibly autoimmune, marked by excessive production of collagen which results in hardening and thickening of body tissues. "IGF-1 and vascular smooth muscle cells are important pathogenic factors in Ssc, as they also seem to be involved in the progression from preclinical stages of Ssc to early stages." (PMID 34063287, 2021). "The levels of IGF-1 are elevated in BALF collected from systemic sclerosis patients as compared with control subjects and increase more in systemic sclerosis patients with abnormal computed tomography, which stimulates fibroblast proliferation." (PMID 30018981, 2018). "We also looked at the function of sirtuins in diseases like systemic sclerosis and how sirtuins may relate to NMSC and IGF-1." (PMID 36993812, 2023).
tendinopathies (7 papers, 2012 to 2024). "Another study reported that EC increased serum levels of Insulin-Like Growth Factor 1 (IGF-1), which is involved in tendon healing and cellular proliferation, making it a therapeutic target for tendinopathy." (PMID 39519397, 2024). "IGF-1 is known to be decreased for approximately 2 weeks in experimentally induced tendinopathy and a beneficial bolstering effect of exogenous IGF-1 on low endogenous IGF-1 production during the early repair phase of tendinopathy has been hypothesized." (PMID 26113022, 2015). "Those that have include versican, in which AS may contribute to changes in ECM structure and function in tendinopathies; lubricin, which is location-dependent; and insulin-like growth factor 1, which is mechanical stress-dependent." (PMID 25888722, 2015). "IRS1 and ERK-1/2 were once demonstrated to be activated in load-induced tenocyte in vivo under insulin-like growth factor 1 (IGF1) signaling during the pathogenesis of overused tendon disorders although no chondro-osteogenesis was observed." (PMID 31065679, 2020).
thyroid-associated ophthalmopathy (7 papers, 2014 to 2024). "We investigated the effect of octreotide, a long-acting somatostatin (SST) analogue, on IGF-1 secretion and its possible mechanism of action in orbital fibroblasts (OFs) from patients with thyroid-associated ophthalmopathy (TAO)." (PMID 33886620, 2021). "In addition, IGF-1R inhibitor showed marked improvement in thyroid-associated ophthalmopathy in humans even though two other human studies did not demonstrate benefits from IGF-1 treatment." (PMID 37242543, 2023). "They concluded that in all patients, except one, with positive expression of FGF, IGF-1 and VEGF showed CAS greater than 5, suggesting in this way an important role of these growth factors in the pathogenesis and severity of Graves' ophthalmopathy." (PMID 25309050, 2014). "In addition, some synergistical effects on cellular metabolism by IGF1 and M22 were also observed in the 2D 3T3-L1 cells as well as in cultured non-Graves’ orbitopathy-related human orbital fibroblasts (n-HOFs), but not in Graves’ orbitopathy-related HOFs (GHOFs)." (PMID 36674625, 2023).
acute coronary syndrome (6 papers, 2018 to 2024). Signs and symptoms related to acute ischemia of the myocardium secondary to coronary artery disease. "A cohort study found that reduced IGF-1 levels were associated with acute coronary syndrome (ACS) development, and increased levels were associated with a lower risk of developing MI." (PMID 38255276, 2024). "Serum IGF-1 level was significantly lower in subjects with acute coronary syndrome and early-onset CVD." (PMID 34394348, 2021). "In some studies, a relation between insulin-like growth factor 1 (IGF-1) and PAPP-A levels in patients with acute coronary syndrome (ACS) was revealed." (PMID 29973962, 2018). "The relationship between IGF-1 levels and major adverse cardiovascular events (MACE) in acute coronary syndrome (ACS) patients remains unclear." (PMID 34851758, 2021).
alopecia (6 papers, 2019 to 2025). Hair loss usually from the scalp. "Understanding the crosstalk between IGF-1 and these signaling networks will be essential to designing personalized, mechanism-based treatments for various forms of hair loss." (PMID 41020895, 2025). "A deeper understanding of the regulatory networks and crosstalk between these miRNAs and IGF-1 could offer significant insights and advances in the development of effective treatments for hair loss." (PMID 41020895, 2025). "Furthermore, primary decreases in GH and IGF-1 have been associated with hair loss and alopecia, while decreases in GH and IGF-1 due to GHRH deficiency have not." (PMID 38540126, 2024). "This suggests that IGF-1 could be a promising therapeutic target for hair loss treatment." (PMID 41020895, 2025). "Insulin‐like growth factor 1 (IGF‐1) is of great significance in hair growth and is involved in various types of alopecia." (PMID 41323822, 2025). "Therapeutic strategies targeting IGF-1 pathways may thus hold promise in arresting or reversing follicular regression in AGA and other hair loss conditions." (PMID 41020895, 2025). "Clinically, primary decreases in GH and IGF-1 have been associated with hair loss and alopecia, while decreases in GH and IGF-1 due to GHRH deficiency have not." (PMID 34948002, 2021). "Absent GHR stimulation, and thus severely decreased IGF-1 levels, is associated with alopecia, telogen effluvium, frontal hairline recession, as well as severe HF structural changes like pili torti et canaliculi and trichorrhexis nodosa." (PMID 34948002, 2021). "According to previous alopecia studies, among the signal proteins present in the skin, keratinocyte growth factor (KGF) and insulin-like growth factor-1 (IGF-1) affect hair growth." (PMID 31088549, 2019). "In AGA, the expression levels of IGF-1 and platelet-derived growth factor (PDGF) in dermal papilla cells (DPCs) are significantly reduced compared to those in individuals without alopecia, implicating their deficiency in the pathogenesis of the disease." (PMID 41020895, 2025). "GHRH deficiency in a Brazilian cohort showed delayed pigmentation, and reported to have youthful hair and no alopecia, even with profoundly decreased serum GH and IGF-1 levels." (PMID 34948002, 2021). "Moreover, the effects of IGF-1 provide further evidence for promoting hair growth and treating alopecia, but a correlative pathway between IGF-1, TGF-β, and DHT has not been reported." (PMID 35209207, 2022).
carpal tunnel syndrome (6 papers, 2016 to 2023). Entrapment of the median nerve in the wrist that is characterized by numbness, tingling and painful movement. "Increased plasma IGF-1 concentrations were associated with both carpal tunnel syndrome and trigger finger in participants from UK Biobank (hazard ratio >1·04, p<0·02)." (PMID 36043126, 2022). "Consistent with the hypothesis that overactive IGF-1 signalling is important in trigger finger and carpal tunnel syndrome, we discovered that IGF-1 plasma concentrations were positively associated with both conditions." (PMID 36043126, 2022). "Finally, we provide evidence to show a significant association between plasma IGF-1 concentrations and both trigger finger and carpal tunnel syndrome, altogether implicating IGF-1 signalling in the pathophysiology of both conditions." (PMID 36043126, 2022). "The long-established co-occurrence of trigger finger and carpal tunnel syndrome might be at least partly explained by a shared germline predisposition, which acts to increase IGF-1 signalling in fibroblasts." (PMID 36043126, 2022). "Several other lines of evidence support the role of IGF-1 signalling in trigger finger and carpal tunnel syndrome." (PMID 36043126, 2022). "We conducted a Cox regression for time to trigger finger and carpal tunnel syndrome diagnosis against plasma IGF-1 concentrations in the UK Biobank cohort." (PMID 36043126, 2022). "Elevated GH levels lead to liver hyperproduction of insulin-like growth factor 1 (IGF-1), causing somatic modifications and systemic manifestations [i.e., cardiovascular disease, osteoarthropathy, metabolic complications, obstructive sleep apnea (OSAS), hyperhidrosis, carpal tunnel syndrome]." (PMID 37829686, 2023).
chordoma (6 papers, 2016 to 2024). Chordomas are rare malignant tumors arising from embryonic remnants of the notochord in axial skeleton. "Interest in insulin-like growth factor 1 (IGF-1), one such growth mediator, in chordomas has been spurred by two features of the IGF family." (PMID 32733369, 2020). "The majority of chordoma samples studied were positive for both IGF-1 and IGF-1R; the level of IGF-1R staining correlated with tumor volume." (PMID 32733369, 2020). "IGF signaling is also important in chordoma tumorigenesis, since IGF-1 and IGF-1R have been detected in 92 and 76% of chordoma tissues, and are absent in benign notochordal cell tumor and fetal notochord." (PMID 30775316, 2019). "First, IGF-1 effects strong mitogenic activity in bone, which, if dysregulated, could accelerate chordoma development." (PMID 32733369, 2020). "Chordomas commonly activate pathways such as EGFR, PDGFβ, IGFR1, IGF1, mTOR, MET, and PI3K and involve chromatin remodeling genes such as ARID1A, PBRM1, and SETD2." (PMID 39193055, 2024). "Emerging literature supports a relationship between IGF-1/IGF-1R expression and prognosis in chordomas." (PMID 32733369, 2020). "Another IHC study detected IGF-1R, IGF-1, and IGF-2 in 76, 90, and 50% of chordomas, respectively, with one-third showing moderate to strong IGF-1R, as in our study, and a significant correlation between IGF-1R staining intensity and primary tumor volume." (PMID 27200287, 2016). "Given that the AKT/mTOR pathway lies downstream of IGF-1/IGF-1R signaling and the success of combined mTOR/IGF-1R inhibition in sarcomas, future clinical trials could benefit from looking at a similar combined approach to chordoma management." (PMID 32733369, 2020).
chronic pancreatitis (6 papers, 2016 to 2024). A chronic inflammatory process causing damage and fibrosis of the pancreatic parenchyma. "Similarly, the combination of ALB with CA19-9 and IGF-1 also performed better than CA19-9 at distinguishing PDAC from chronic pancreatitis." (PMID 36969742, 2022). "Given that chronic pancreatitis is a risk factor for PDAC and that an inflammatory environment can directly promote tumor initiation, we employed here TD protocols P2 and a third protocol (P3, based on a combination of IGF-1, SCF and transferrin) for the generation of insulin-expressing cells." (PMID 34572891, 2021). "CA 19–9, carcinoembryonic antigen (CEA), C-reactive protein, albumin, insulin growth factor-1 (IGF-1) and IGF binding protein-3 were measured using routine clinical analyzers in a cohort of 47 pancreatic adenocarcinoma, 20 chronic pancreatitis and 15 healthy controls." (PMID 26808421, 2016).
coronary atherosclerosis (6 papers, 2012 to 2025). Atherosclerosis of the coronary vasculature. "In summary, we report here that IGF-1 administered over 6 months decreased coronary atherosclerosis and promoted features of stable atheroma in FH pigs, without evidence of a tumorigenic effect." (PMID 36602878, 2023). "To obtain further insights into the effects of IGF-1 on coronary atherosclerosis, we performed an exploratory analysis of advanced plaques from FH females, using the newly developed technology spatial transcriptomics." (PMID 36602878, 2023). "Furthermore, downregulated FOSB and MMP9 were found under the treatment of Insulin-like growth factor 1 that reduced reduces coronary atherosclerosis." (PMID 40486911, 2025). "The IGF-1–induced increase in vessel lumen and reduction in relative atheroma indicate that IGF-1 reduces coronary atherosclerosis." (PMID 36602878, 2023).
diabetes insipidus (6 papers, 2011 to 2025). A disorder characterized by excretion of large amounts of urine, accompanied by excessive thirst. "Central diabetes insipidus remained in all survivors, and four (40%) of them had concomitant partial anterior pituitary hormone deficiency, primarily of growth hormone and insulin-like growth factor-1." (PMID 35378836, 2022).
eating disorder (6 papers, 2012 to 2023). A broad group of psychological disorders with abnormal eating behaviors leading to physiological effects from overeating or insufficient food intake. "However, IGF-1 deficiency can also be secondary to existing various chronic diseases, eating disorders and some inflammatory diseases." (PMID 34445772, 2021). "Future studies need to address effects of physical activity and exercise on levels of hormones such as IGF-1 and cortisol among patients with eating disorders." (PMID 22470294, 2012).
end-stage renal disease (6 papers, 2008 to 2023). "Insulin like growth factor binding protein (IGFBP) is elevated in patients with end stage renal failure, resulting in reduced bioactivity of insulin like growth factor (IGF-1)." (PMID 24711748, 2014).
endotoxemia (6 papers, 2015 to 2025). "In rats with thermal injury and endotoxemia, treatment with IGF-1/IGFBP-3 improved villous height and cell count per villus by reducing epithelial apoptosis and promoting proliferation." (PMID 40724799, 2025). "Our animal experiment showed that external administration of IGF-1 reduced endotoxemia in liver cirrhotic rats via up-regulating occludin and claudin-1 expression in intestines." (PMID 26152281, 2015). "IGF-1 is able to break the vicious circle of endotoxemia and intestinal barrier dysfunction." (PMID 26152281, 2015). "Interestingly, animal model studies suggest that administration of insulin-like growth factor I (IGF-1) in cirrhotic rats can effectively downregulate the expression of tumor necrosis factor alpha (TNF-α) and decisively reduce portal vein pressure, bacterial translocation, and endotoxemia." (PMID 30930689, 2019).
gastric adenocarcinoma (6 papers, 2012 to 2025). "In another study of 26 patients with gastric adenocarcinoma (M/F = 15/11, mean age 65 years), serum IGF-1 levels were measured." (PMID 41303367, 2025). "Incubation of gastric adenocarcinoma cells with different insulin, IGF-1 or IGF-2 concentrations prior to induction of apoptosis demonstrated concentration-dependent protection." (PMID 34554347, 2022). "High tumour IGF1 and IGF2 expression, IGF2 is the 25th most over-expressed gene in gastric adenocarcinoma, implies local IGF-1 and IGF-2 synthesis." (PMID 34554347, 2022). "Proliferative effects of insulin on gastric adenocarcinoma cells were compared to those of IGF-1 and IGF-2." (PMID 34554347, 2022). "The relative EC50 values for insulin-stimulated protein phosphorylation in gastric adenocarcinoma cells, 1.2–5 ngml−1 (0.2–2.6 nM) were similar to those of IGF-1 and IGF-2." (PMID 34554347, 2022). "Expression of insulin receptor isoform A, for which IGF-1 and IGF-2 have higher affinities than they have for isoform B, by gastric adenocarcinoma cells makes this supposition plausible." (PMID 34554347, 2022). "INS, IGF1 and IGF2 mRNAs were measured in a separate cohort of 1065 gastric adenocarcinomas by microarray hybridisation." (PMID 34554347, 2022). "Tumour synthesis coupled with demonstration that IGF-1 and IGF-2 stimulate gastric adenocarcinoma cell growth and survival, suggests potential autocrine activity." (PMID 34554347, 2022). "Relatively higher expression of insulin receptor isoform B, for which insulin has considerably higher affinity than IGF-1 or IGF-2 has, was apparent in metastatic gastric adenocarcinoma cells." (PMID 34554347, 2022). "Dependence of gastric adenocarcinoma cell survival upon insulin receptor but not type I IGF receptor indicates that IGF-1 and IGF-2 promote cell survival through the insulin receptor." (PMID 34554347, 2022). "Knockdown of MMP11 expression was observed to inhibit the proliferation and invasion of human gastric adenocarcinoma (GAC) cells, and it was suggested that the down-regulated Insulin-like growth factor-1 (IGF-1) signaling pathway might be responsible for this phenomenon." (PMID 31940762, 2020).
Graves disease (6 papers, 2019 to 2025). Graves' disease is an autoimmune disorder that leads to overactivity of the thyroid gland (hyperthyroidism).It is caused by an abnormal immune system response that causes the thyroid gland to produce too much thyroid hormones. "Previous studies in a murine model of Graves’ disease have shown that diosgenin can inhibit the proliferation of thyroid cells by inhibiting the expression of IGF-1, NF-κB, cyclin D1, and PCNA and alleviate goitre." (PMID 33737640, 2021).
head and neck cancer (6 papers, 2010 to 2025). A primary or metastatic malignant neoplasm affecting the head and neck. "Observational data has shown that higher prediagnostic serum IGF-1 predicted progression and a higher rate of developing a second primary tumor in head and neck cancer patients." (PMID 31569808, 2019). "This observational study cannot claim causality, but it supports further evidence for the hypothesis that the IGF-1 pathway is involved in development of epithelial cancers, as was also demonstrated in a study for second primary tumours in patients with a head and neck cancer." (PMID 25047238, 2014).
hypertriglyceridemia (6 papers, 2015 to 2021). A laboratory test result indicating elevated triglyceride concentration in the blood. "A retrospective study showed an improvement of hypertriglyceridemia and HDL cholesterol levels after normalization of IGF-1/GH levels achieved with either surgery or medical therapy, although this did not occur in all patients with controlled disease." (PMID 32117056, 2020).
Intellectual disability (6 papers, 2012 to 2025). "Rare mutations in the human IGF1 result in severe growth inhibition and intellectual disability." (PMID 39482999, 2025).
pheochromocytoma (6 papers, 2012 to 2023). "In the present report, we have studied the effect of TSN on the proliferation of rat pheochromocytoma (PC12) cells induced by IGF-1 and its underlying mechanisms." (PMID 30213025, 2018). "Tumors that have been reported to cause NICTH include malignancies associated with insulin receptor antibodies, tumor necrosis factor (TNF), interleukin (IL) -1 or -6; pheochromocytoma associated with excess catecholamine production; and paraneoplastic production of IGF-1 or IGF-2." (PMID 24934576, 2014). "By the comparison of hypoxia- and Ras-associated pheochromocytoma, we have found that enhanced insulin like growth factor 1 signaling may be responsible for the activation of Src homology 2 domain containing transforming protein 1, the main co-factor of RET." (PMID 23106811, 2012). "IGF1 maintains the phenotype of the tumor and allows the transformed murine pheochromocytoma cells to survive." (PMID 32694937, 2020). "NICTH has also been reported in conjunction with paraneoplastic production of insulin receptor antibodies, tumor necrosis factor (TNF), interleukin (IL) -1 and -6, catecholamine (pheochromocytoma) and IGF-1." (PMID 24934576, 2014). "To obtain insight into CEPO and IGF-1 combination signaling, we examined immediate early gene (IEG) expression after treatment with CEPO, IGF-1, or CEPO + IGF-1 in rat pheochromocytoma (PC-12) cells and found that combining CEPO and IGF-1 produced a synergistic increase in IEG expression." (PMID 37763230, 2023).